HOXA-AS3 (HOXA cluster antisense RNA 3)
Synonyms: HOXA6as
Gene: Long non-coding RNA gene on chromosome 7 (27,129,977 to 27,155,928, forward strand). Ensembl gene ENSG00000254369.
Diseases named in the same sentence as HOXA-AS3 in open-access papers:
HOXA-AS3 is named in the same sentence as 24 diseases in open-access papers, as found by Europe PMC text mining. Sharing a sentence is not in itself a finding about the gene and the disease. The quoted sentences say what the papers report.
glioma (12 papers, 2017 to 2023). A benign or malignant brain and spinal cord tumor that arises from glial cells (astrocytes, oligodendrocytes, ependymal cells). "HOXA-AS3 was upregulated in glioma tissues and cells, and its high-expression was associated with tumor grade and poor prognosis in patients." (PMID 28881797, 2017). "HOXA-AS3 is a risk factor in a variety of tumors, including glioma." (PMID 34408772, 2021). "HOXA-AS3 was reported up-regulated in glioma tissue and positively related with poor prognosis in glioma patients." (PMID 37403043, 2023). "Consistent with previous research findings, the other 7 lncRNAs that we have identified in our risk model, have all been reported to play significant biological roles in gliomas, particularly HOXA-AS3, LINC00665, MIR155HG, and NEAT1." (PMID 37403043, 2023). "HOXA-AS3 was highly expressed in glioma tissues and cell lines (LN229, U251, SNB19, U87, U138, and H4) and was closely associated with poor prognoses such as worse overall survival and pathological grade." (PMID 35986859, 2022). "HOXA-AS3 was previously shown to function as an oncogene and was upregulated in various cancers including glioma tissues, NSCLC, and HCC." (PMID 33643896, 2020). "In previous studies, HOXA-AS3 was found to be upregulated in glioma tissues and cell lines, and high expression of HOXA-AS3 is associated with poor prognosis in patients with glioma." (PMID 31615976, 2019). "HOXA-AS3 acts as an oncogene in glioma by increasing cell proliferation, inhibiting apoptosis, and promoting cell migration." (PMID 31615976, 2019). "HoxA-AS3 (HOXA cluster antisense RNA 3) was originally identified as an upregulated molecule in glioma patients, which is located on 7p15.2 and is 3992 nt in length." (PMID 29535782, 2018). "Furthermore, HOXA-AS3 has provided promising values in the diagnosis, prognosis, and therapeutic strategies of several diseases such as liver cancer, glioma, lung cancer, oral cancer, gastric cancer, and even atherosclerosis." (PMID 35986859, 2022). "For HOXA-AS3, though it has not been identified in CA before, the up-regulation of HOXA-AS3 was reported to be associated with tumor progression and poor prognosis in glioma." (PMID 31470869, 2019). "The mechanism by which HOXA-AS3 promotes glioma cell growth will be verified in the next work." (PMID 28881797, 2017). "Furthermore, in vitro and in vivo knockdown assays were performed to determine the functions of HOXA-AS3 in glioma tumorigenesis and progression." (PMID 28881797, 2017). "Our findings provide a new perspective that HOXA-AS3 may acts as an oncogene in glioma progression and a new target for treatment of glioma." (PMID 28881797, 2017). "However, further studies are required to clarify the possible mechanism by which HOXA-AS3 regulates glioma cell biological function." (PMID 28881797, 2017). "Moreover, knockdown of HOXA-AS3 inhibited glioma cells tumorigenesis in vivo." (PMID 28881797, 2017). "In addition, to determinate whether HOXA-AS3 inhibits the growth of glioma cell specifically, we performed knockdown assay in two normal glial cells (HA and HAC)." (PMID 28881797, 2017). "Conversely, other transcripts, such as HOXA‐AS3, HOXB‐AS3 and HOXB9, were upregulated only in approximately 20% of IDHwt glioma samples." (PMID 33720519, 2021). "There is clear evidence that HOXA-AS3 can function as a ceRNA in the context of HCC, glioma, and atherosclerosis." (PMID 33602223, 2021). "For example, suppression of HOXA-AS3 in glioma tumor models showed an apparent reduction in glioma tumor weight and size, suggesting the promising therapeutic potential of targeted-HOXA‐AS3 for glioma." (PMID 35986859, 2022). "Moreover, GEPIA database analyses revealed that expression levels of RMRP, HOXA-AS3, and CASC9 were notably up-regulated in glioma tissues than in normal tissues." (PMID 34657141, 2021).
glioma (continued). "Given the association of tumor recurrence and drug resistance, expression patterns of RMRP, HOXA-AS3, and CASC9 were examined in tumor tissues isolated from glioma patients without any treatment (n = 20) and glioma patients suffered from recurrence post-treatment (n = 12)." (PMID 34657141, 2021).
lung carcinoma (3 papers, 2019 to 2022). "Lastly, investigations into the details of how HOXA-AS3 affects the response of lung cancer cells to other chemotherapeutic agents should be performed to provide a deeper understanding of the underlying molecular details of HOXA-AS3-mediated drug resistance." (PMID 31615976, 2019). "The developed xenograft mice model confirmed that HOXA-AS3 knockdown increased cisplatin effectiveness in lung cancer." (PMID 35986859, 2022). "Another study found that HOXA-AS3 promoted proliferation, migration and invasion in A549 lung carcinoma cell line and tumor growth in vivo, where it was found in both the nucleus and the cytoplasm, consistent with our data in HT-29 cells." (PMID 34280202, 2021).
gastric cancer (2 papers, 2022 to 2023). A primary or metastatic malignant neoplasm involving the stomach. "HOXA-AS3 was upregulated in gastric cancer cell lines (MGC-803, AGS, MKN45, SGC7901, and HGC-27) and tissues." (PMID 35986859, 2022). "Furthermore, in oncogenic contexts, HOXA-AS3 has been reported to be upregulated in gastric cancer tissues and cell lines and is correlated with tumour size, lymph node status and invasion depth." (PMID 37752588, 2023).
glioblastoma (2 papers, 2017 to 2020). The most malignant astrocytic tumor (WHO grade IV). "The newly identified HOXA‐AS3/mir‐455‐5p/USP3 pathway offers important clues to understanding the key mechanisms underlying the action of lncRNA HOXA‐AS3 in glioblastoma." (PMID 32918360, 2020).
lung adenocarcinoma (2 papers, 2021 to 2023). A carcinoma that arises from the lung and is characterized by the presence of malignant glandular epithelial cells. "In this study, we discovered that HOXA-AS3 was upregulated in OS tissues and cell lines, which was consistent with the findings in lung adenocarcinoma tissues and A549 cells." (PMID 37752588, 2023). "Similarly, HOXA-AS3 was markedly upregulated in lung adenocarcinoma tissues and cells and promoted cancer cell progression." (PMID 34698001, 2021).
lung fibrosis (2 papers, 2020 to 2022). "Overexpression of Hoxaas3 promoted fibrogenesis, whereas Hoxaas3 inhibition attenuated lung fibrosis both in vitro and in vivo, through regulation of miR-450b-5p." (PMID 32848140, 2020).
non-small cell lung carcinoma (2 papers, 2021 to 2023). A group of at least three distinct histological types of lung cancer, including non-small cell squamous cell carcinoma, adenocarcinoma, and large cell carcinoma. "Studies have revealed that HOXA-AS3 plays a tumourigenic role in non-small-cell lung carcinoma and glioblastoma." (PMID 37752588, 2023). "There is also evidence that HOXA-AS3 can mediate cisplatin resistance, making it a viable therapeutic target in non-small cell lung cancer (NSCLC)." (PMID 33602223, 2021). "Moreover, HOXA-AS3 has been identified to modulate the resistance of non-small-cell lung carcinoma cells to cisplatin." (PMID 37752588, 2023).
osteosarcoma (2 papers, 2023 to 2024). A usually aggressive malignant bone-forming mesenchymal neoplasm, predominantly affecting adolescents and young adults. "Overexpression of HOXA-AS3 was found in osteosarcoma tissues and was linked to poor outcomes." (PMID 39019995, 2024). "However, the role and potential mechanism of HOXA-AS3 in osteosarcoma (OS) remain unknown." (PMID 37752588, 2023).
pancreatic cancer (2 papers, 2021 to 2022). "HOXA-AS3 was overexpressed in pancreatic cancer tissues and Panc-1, Aspc-1, sw1990, and Bxpc-3 cells and was closely bound up with worse prognosis, aggressive TNM stage, and lymph node metastasis." (PMID 35986859, 2022). "Besides, downregulation of HOXA-AS3 by CRISPR-dCas9 has also been indicated to impair the tumor growth of pancreatic cancer Panc-1 cells in vivo." (PMID 35986859, 2022). "Nevertheless, the molecular mechanism of HOXA-AS3 in pancreatic cancer (PC) progression remains unknown." (PMID 34659534, 2021). "We first tested the expression levels of HOXA-AS3 in five cell lines [four pancreatic cancer cell lines (Panc-1, Bxpc-3, Aspc-1, and Sw1990)] and one normal pancreatic dutal cell (HPDE) and found that the expressions of HOXA-AS3 were relatively higher in pancreatic cancer cell lines." (PMID 34659534, 2021).
pulmonary arterial hypertension (2 papers, 2022 to 2023). Pulmonary arterial hypertension (PAH) is a group of diseases characterized by mean pulmonary artery pressure >20 mmHg and elevated pulmonary arterial resistance leading to right heart failure. "For example, H3K9Ac acetylation involving activation of the promoter partially contributes to the up-regulation of Hoxaas3 in pulmonary hypertension." (PMID 36818559, 2023). "HOXA-AS3 was also overexpressed hypoxia-treated human pulmonary artery smooth muscle cells (HPASMCs), which was regarded as in vitro model of pulmonary arterial hypertension (PAH)." (PMID 35986859, 2022).
bladder cancer (1 paper, 2020). "Therefore, HOXA-AS3 may be a novel therapeutic target for treating bladder cancer." (PMID 33643896, 2020).
chordoma (1 paper, 2021). Chordomas are rare malignant tumors arising from embryonic remnants of the notochord in axial skeleton. "The genes HOXB7, HOXB13, and HOXA-AS3 were detected among the upregulated genes in recurrent chordomas." (PMID 34330313, 2021).
colorectal cancer (1 paper, 2022). A primary or metastatic malignant neoplasm that affects the colon or rectum. "Overexpression of HOXA-AS3 has been reported in colorectal cancer tissues and SW480, SW620, HCT116, COLO205, and LOVO cells." (PMID 35986859, 2022).
hepatocellular carcinoma (1 paper, 2022). A malignant tumor that arises from hepatocytes. "It was found that HOXA-AS3 expression was markedly upregulated in hepatocellular carcinoma cells (Hep3B, SNU-387, Li-7, SMMC-7721, HepG2, Huh7, and HCC-LM3) and tissues." (PMID 35986859, 2022).
lung squamous cell carcinoma (1 paper, 2019). "To investigate the potential role of HOXA-AS3 in NSCLC, we first used the StarBasev. project to analyze the level of HOXA-AS3 in LUSC (lung squamous cell carcinoma)." (PMID 31615976, 2019).
viral infection (1 paper, 2021). "To study the functions of HOXA-AS3 and HOXB-AS3 during early steps of stem cell differentiation, we established dCas9-expressing H9 hESCs, using viral infection of Tet-dependent inducible versions of the dCAS9 and dCas9-VP64." (PMID 34280202, 2021).
tumor (9 papers, 2019 to 2026). "Furthermore, the expression of HOXA-AS3 in tumour tissues of the control group was significantly higher than that in the sh-HOXA-AS3 group." (PMID 37752588, 2023). "Xenograft tumor growth increased with the overexpression of HOXA-AS3." (PMID 34988230, 2021). "HOXA-AS3 affects the epithelial-to-mesenchymal transition (EMT) of OS, which plays a crucial role in tumour formation and progression." (PMID 37752588, 2023). "HOXA-AS3 has also been identified as a novel target in NSCLC patients owing to its ability to downregulate HOXA3 and to thereby modulate tumor cell resistance to cisplatin treatment." (PMID 33602223, 2021). "To further investigate the relationship between HOXA-AS3 and HOXA3, we performed western blotting and qPCR to detect the expression of HOXA-AS3 or HOXA3 in tumor tissues from nude mice." (PMID 31615976, 2019).
cancer (6 papers, 2017 to 2021). A tumor composed of atypical neoplastic, often pleomorphic cells that invade other tissues. "KEGG pathway analysis revealed that HOXA-AS3 is highly correlated with genes involved in pathways in cancer, focal adhesion, cell cycle, ECM-receptor interaction, apoptosis and DNA replication." (PMID 28881797, 2017). "CRISPR may provide an alternative approach to treat cancer by targeting HOXA-AS3." (PMID 34659534, 2021). "Besides, we revealed that knockdown of HOXA-AS3 inhibits tumorigenesis and cancer progression." (PMID 29899328, 2018).
HOXA-AS3 also shares sentences with these, for which no sentence is quoted: atherosclerosis (2 papers); endometriosis (1); liver cancer (1); oral cancer (1); primary immunodeficiency (1); pulmonary hypertension (1).